CD47 (CD47 molecule)
Diseases named in the same sentence as CD47 in open-access papers (continued):
Sharing a sentence is not in itself a finding about the gene and the disease.
hematologic malignancies (continued). "CD47 has shown potent anticancer potentials in a variety of hematologic malignancies, including MDS and AML, and a number of CD47-related antibodies or target drugs have emerged." (PMID 35433462, 2022). "A CD47 blocking antibody, TTI-621 (Trillium), is also in clinical trials for hematological malignancies and selected solid tumors (clinicaltrials.gov identifier: NCT02663518)." (PMID 32273348, 2020). "As of October 2023, there are no publicly published clinical trials on CD47 small-molecule inhibitors or ADC specifically for hematologic malignancies." (PMID 39040441, 2024). "GS‐0189 was designed as an alternative to magrolimab, an anti‐CD47 monoclonal antibody (mAb) in clinical development in hematologic malignancies and solid tumors, as it had been found not to impact red blood cells in preclinical experiments." (PMID 37206279, 2023). "Since no clinical trials on CD47 small-molecule inhibitors or antibody–drug conjugates for hematologic malignancies are publicly available, only the first three categories will be discussed." (PMID 36726125, 2023). "However, as CD47 monoclonal antibodies such as magrolimab have demonstrated an absence of efficacy in pivotal clinical trials for hematologic malignancies and have exhibited significant hematologic toxicity, clinical research targeting CD47 faces challenges." (PMID 41354057, 2025). "Thus, Development of anti-CD47 based therapeutics with no or limited binding to RBCs is an attractive direction for both hematological malignancies and solid tumors treatment." (PMID 36593962, 2023). "Therefore, CD24 might play a significant role in certain hematological malignancies, such as MCL and FL, in which the well-known immune checkpoint CD47 may be less relevant." (PMID 35625912, 2022). "Additionally, the anticancer activity of anti-CD47 antibodies depends on CS1 glycoprotein antigen (SLAMF7) phagocytic signaling, which is generally absent in solid cancers but is expressed in hematological malignancies." (PMID 40589735, 2025).
infection (50 papers, 2009 to 2025). The state of being infected such as from the introduction of a foreign agent such as serum, vaccine, antigenic substance or organism. "This time course data provides valuable insights into how CD47 expression correlates with the window of enhanced susceptibility to secondary infection, which is typically observed between days 5–10 post-infection with influenza virus." (PMID 38693120, 2024). "CD47, a gene encoding an integrin-associated protein, was up-regulated in response to infection by both HPIV3 and RSV in our study." (PMID 23742656, 2013). "Furthermore, CD47 down-regulation leads to better resolution post-infection and it has been shown that deficiency in CD47 results in lower bacterial burdens and increased survival of mice after infection." (PMID 29755958, 2018). "To this end, we infected C57BL/6 mice intravenously with 2 × 106 PFU VSV and treated mice intraperitoneally with 100 μg of anti-CD47 antibodies or a control (isotype) at 2, 3, and 4 days post-infection (dpi)." (PMID 40573933, 2025). "These primary islet DKO cells were transduced to express a wide range of CD47 levels by using lentiviral particles in different multiplicities of infection." (PMID 37156915, 2024). "Taken together, our results demonstrate that both airway epithelial CD47 and S. aureus FnBP are essential for the development of super-infection." (PMID 38693120, 2024). "To further solidify our findings, we employed a combination of FoxJ1+ cell-specific CD47 gene-deletion mice and a FnBP mutant strain of S. aureus in the context of super-infection." (PMID 38693120, 2024). "To investigate the function of CD47 in super-infection, we reduced CD47 expression by transfecting airway epithelial cells with lentiviral shRNA targeting the CD47 gene." (PMID 38693120, 2024). "In a super-infection model with S. pneumoniae, the treatment of CD47 shRNA and α-hCD47 antibodies exhibited comparable protective effects on paracellular permeability and TEER in HBECs." (PMID 38693120, 2024). "As CD47 is ubiquitously expressed, understanding the contributions of specific CD47-expressing cell types during super-infection is crucial for gaining detailed mechanistic insights." (PMID 38693120, 2024). "Among these human-unique sEV proteins, CD47 is a leukocyte surface antigen important for immune cell recruitment to the site of infection." (PMID 37106610, 2023). "Teeming presence of C. albicans was observed in the PCM@NP group and the anti‐CD47 group after infection, whereas anti‐CD47‐PCM@NP group manifested two orders of magnitude fewer colony‐forming units (CFU)." (PMID 36683161, 2023). "As an important marker in immune responses, CD47 plays a controversial role in the infection process, raising potential concerns for interferences during CD47‐targeting therapies." (PMID 36683161, 2023). "Earlier, we reported that effector NK cells were significantly depleted in LCMV Arm with infected Cd47−/− mice as early as on day 3 post-infection, which can lead to increased viral titer." (PMID 36105746, 2022). "CD47 was dispensable in the initial CD8+ T cells response to LCMV-Arm infection based on the phenotype on the 8th day of infection." (PMID 36105746, 2022). "Overall, oAd-mCD47nb-Fc infection can block CD47 and enhance phagocytosis through CD47 inhibition, as well as inducing immunological cell death." (PMID 35837100, 2022). "Collectively, these results further underscore our observation that Vpu-mediated CD47 downregulation potentiates phagocytosis of infected T cells by MDMs and, consequently, promotes increased productive infection of MDMs." (PMID 34425695, 2021). "We also show that CD47 modulation by Vpu promotes enhanced capture and phagocytosis of T cells by monocyte-derived macrophages (MDMs), which ultimately leads to productive infection of MDMs." (PMID 34425695, 2021).
infection (continued). "Experiments directly comparing WT and dU WITO-infected target T cells support the notion that enhanced phagocytosis of infected T cells by MDMs following Vpu-mediated CD47 downregulation facilitates productive infection of macrophages." (PMID 34425695, 2021). "Vpu facilitates productive infection of macrophages by enhancing phagocytosis of infected T cells through CD47 downregulation." (PMID 34425695, 2021). "Salmonella typhi lacking potent inducer of TLR was found to have reduced CD47 expression during infection suggesting that TLR activation is important for CD47 upregulation during infection." (PMID 32882841, 2020). "This enhanced immune response surprisingly led to wide dissemination of the infection, resulting in increased morbidity and mortality in the CD47 knockout mice." (PMID 32882841, 2020). "Ki-67 levels in Cd47−/− NK cells on day 46 post-Cl-13 infection were significantly elevated, indicating increased proliferation of Cd47−/− NK cells." (PMID 30643501, 2018). "Comprehensive pairwise comparison of NK cells showed significant upregulation of multiple genes in WT relative to Cd47−/− mice upon infection (2, 135 genes in WT vs. 486 genes Cd47−/− NK cells)." (PMID 30643501, 2018). "Effector genes including Hif1a (HIF-1α), Irf7 (IRF7), Gzmb (granzyme B) and Gzmc (granzyme C), together with Cd47 as a control, were significantly downregulated in Cd47−/−, less than in WT NK cells upon infection." (PMID 30643501, 2018). "Expanded Th1, Th2, and Th17 populations were found in spleens of mice infected with Candida albicans and associated with altered inflammatory gene expression and impaired control of the infection in Cd47−/− mouse kidneys." (PMID 30643501, 2018). "Consistent with these viral titers, NK1.1+ NKp46+ cell numbers in the spleens of Cd47−/− mice were significantly decreased on day 25 post-infection." (PMID 30643501, 2018). "Viral titers still trended higher in the Cd47−/− mice on day 25 post-infection (1.5-fold more in Cd47−/− than WT)." (PMID 30643501, 2018). "Consistent with the data from day 25 post infection, intracellular Ki-67 levels were significantly higher in Cd47−/− NK cells at day 46 post infection." (PMID 30643501, 2018). "Conversely, infection resulted in significant downregulation of more genes in Cd47−/− than in WT NK cells compared to the corresponding naïve NK cells (1, 136 genes in Cd47−/− vs. 447 genes in WT)." (PMID 30643501, 2018). "At 3 days post infection, this was driven by a decrease in CD47 specifically on inflammatory lung neutrophils." (PMID 29755958, 2018). "Immune responses to infection in Cd47−/− mice support this dual role for CD47 and identified alterations in functional responses of neutrophils, macrophages, and T cells." (PMID 30643501, 2018). "LPS-treated or E. coli-infected cd47−/− mice had reduced levels of pro-inflammatory cytokines and neutrophil infiltration and, therefore, were protected against lung injury during infection." (PMID 26813769, 2016). "cd47-/- mice inoculated with C. albicans died as early as 4 day post-infection (PI) and suffered 100% mortality by 14 days PI." (PMID 26010544, 2015). "cd47-/- mice had enlarged kidneys compared with the WT during the entire course of infection except day 1 PI." (PMID 26010544, 2015). "CD47 expression on leukocytes and endothelium is thereby critical for immune cells to localize to a site of infection and for T cell activation." (PMID 26010544, 2015). "Despite normal fungal colonization at earlier times, cd47-/- mice at four days post-infection had increased colonization of brain and kidneys accompanied by stronger inflammatory reactions." (PMID 26010544, 2015). "CD47 can regulate chemotaxis, adhesion, cytophagy and migration of neutrophils and activate the host inflammatory response against infection by binding to integrin." (PMID 25658794, 2015).
infection (continued). "Surprisingly, although SIRPα was undetectable in the liver of uninfected mice, the hepatic iNKT-cell response to infection was also impaired in CD47−/− mice." (PMID 19877019, 2010). "In a recent study on IAV co-infections with Staphylococcus aureus, the authors showed that the viral infection induces increased presence of the attachment receptor CD47 on the cell surface, thereby promoting attachment of and severity of infection with S. aureus." (PMID 40615578, 2025). "So, is CD47-SIRPα-promoted Aβ secretion beneficial or harmful during infection?" (PMID 40185975, 2025). "Notably, the specific involvement of CD47 in airway epithelium during super-infection remains unexplored." (PMID 38693120, 2024). "Another interesting observation, which was not followed in more detail, was the fact, that AdWT and AdWT combination with CD47i did not increase phagocytosis of A673 cells, adding up to our observation of less CD47 induction after AdWT-infection as compared to XVir-infection." (PMID 38357194, 2024). "Furthermore, we inhibited CD47 protein function by pre-incubating cells with α-hCD47 neutralizing antibodies before super-infection." (PMID 38693120, 2024). "Subsequently, we investigated whether the presence of airway epithelial CD47 or myeloid CD47 is essential for super-infection." (PMID 38693120, 2024). "Next, we examined the efficacy of antibody-mediated CD47 blockade in inhibiting super-infection." (PMID 38693120, 2024). "Subsequently, we assessed the impact of CD47 knockdown on the response to super-infection by measuring paracellular FITC-dextran permeability and TEER at 3 dpi, which revealed a substantial attenuation of these effects in both HNECs and HBECs following CD47 shRNA treatment." (PMID 38693120, 2024). "Patients specifically under infection or chronic inflammatory conditions may become severely anemic upon CD47 blockade." (PMID 37063284, 2023). "Initially, our speculation revolved around the possibility that HIV proteins released during infection may trigger the upregulation of CD47 expression on NK cells." (PMID 38037074, 2023). "In addition, the mean survival time of the anti‐CD47‐PCM@NP group after infection (14.7 d) was significantly longer than that of the anti‐CD47 (7.8 d) and PCM@NP (6.9 d) groups." (PMID 36683161, 2023). "CD47 can play both promotive and protective roles based on the type of infection in mice." (PMID 36105746, 2022). "Therefore, Cd47−/− mice have been a successful model to study the role of CD47 in immune homeostasis after introducing experimental infections and tumors." (PMID 36105746, 2022). "Such a decrease in CD47 expression allows for enhanced phagocytosis of infected T cells by macrophages, which ultimately leads to productive infection of this myeloid cell subset even with HIV strains that would otherwise be weakly M-tropic (i.e., T/F viruses)." (PMID 34425695, 2021). "Putting our observation in this context, we investigated whether Vpu-mediated CD47 downregulation would facilitate macrophage infection by promoting phagocytosis of HIV-1-infected CD4+ T cells." (PMID 34425695, 2021). "The OV-αCD47-G1- and OV-αCD47-G4-infected U251T2 GBM cells released appreciable and similar amounts of anti-CD47 antibody as early as 12 h post infection (hpi), and the yields reached near-maximum levels over 5 μg/ml at 24 hpi and peak levels over 6 μg/ml in culture at 48 hpi." (PMID 34625564, 2021). "Therefore, CD47 is an immune checkpoint molecule that can regulate both innate and adaptive immunity thereby influencing the outcome of an infection." (PMID 32882841, 2020). "Most studies on the role of CD47 during infection employed the used of CD47 knockout mice." (PMID 32882841, 2020). "All these studies unanimously points out the immunosuppressive role of CD47 upon infection." (PMID 32882841, 2020). "With such an effect during infection, the blockade of CD47 using anti-CD47 antibody could be a potential therapeutic target for wide range of infections." (PMID 32882841, 2020).
infection (continued). "With such an immunotherapeutic effect of anti-CD47 antibody, one could speculate that the treatment of the anti-CD47 may also increase the interferon response and APCs activation during infection." (PMID 32882841, 2020). "Indeed, several studies on the genetic inactivation or blockade of CD47 demonstrate therapeutic potential during infection." (PMID 32882841, 2020). "Therefore, there is a potential to rationale CD47 blockade in treating infections due to bacteria and multidrug resistant bacterial strains." (PMID 32882841, 2020). "Notably, SFB colonization significantly decreased CD47 expression on infected lung neutrophils as early as 18 h post infection and continued through 3 days post infection." (PMID 29755958, 2018). "CD47 expression at 18 h post infection follows a similar trend." (PMID 29755958, 2018). "Comprehensive comparison of GSEA following infection showed significant downregulation of naïve (NES= −1.73, p < 0.001), early effector (NES= −1.96, p < 0.001) and interferon (NES = −2.09, p < 0.001) signature genes in CD47-deficient compared to WT NK cells." (PMID 30643501, 2018). "For example, patients, especially those under chronic inflammatory conditions or infection, may become severely anemic upon CD47 blockade." (PMID 28077173, 2017). "Furthermore, E. coli K1 up-regulated CD47 on dendritic cells in a mouse meningitis model, thereby increasing tolerance to infection." (PMID 26010544, 2015). "However, in a remarkable instance of co-evolution, the increased levels of accessible CD47 also allow for a more efficient attachment of Staphylococcus aureus to the virally infected cell, and hence exacerbate the impact of the bacterial secondary infection." (PMID 40615578, 2025). "However, CD47 plays both host protective and detrimental role depending on the type of infection." (PMID 32882841, 2020). "However, the use of anti-CD47 antibody in other infections remains to be investigated." (PMID 32882841, 2020). "Furthermore, increased expression of CD47 on reticulocytes was shown to prevent phagocytosis and clearance of infected cells, thus allowing unchecked multiplication and infection of new red blood cells." (PMID 29515528, 2018). "Untreated tumors exhibited greater variability in their expression of CD47 and surface CRT, with the impact of NDV infection less apparent than during in vitro infections." (PMID 41322194, 2025). "Upon infection of these cell lines with NL 4-3 ADA WT HIV-1, we observed downregulation of CD47 by 40% on JC47-hCD47 cells, but we observed a downregulation of only 10% on those expressing the chimeric JC47-cCD47." (PMID 34425695, 2021). "To identify CD47-dependent gene expression during LCMV infection we infected WT and Cd47−/− mice with acute LCMV Armstrong virus and performed global transcriptome analysis of splenic NK cells at day 8-post infection, using naïve mice as controls." (PMID 30643501, 2018). "We found that CD47 was required for the optimal production of IFN-γ from splenic iNKT cells following exposure to the αGalCer analogue PBS-57 and in vivo infection of mice with Leishmania donovani." (PMID 19877019, 2010). "As B16-F10 exhibited the largest increase in CD47 and expression of GFP following NDV-GFP infection, we sought to investigate whether this trend would be observed in vivo." (PMID 41322194, 2025). "A previous study has highlighted the crucial role of CD47 as an “eat me” signal critical for macrophage clearance of neutrophils that have ingested S. aureus, leading to increased infection in the absence of CD4763." (PMID 38693120, 2024). "Intriguingly, in contrast to this observation, S. aureus single infection failed to induce CD47 expression in both in vitro and in vivo settings." (PMID 38693120, 2024). "Infection-induced upregulation of PD1 in both WT and Cd47−/− CD8+ T cells was comparable." (PMID 36105746, 2022). "In the immune and infection context, THBS1 and its receptor, CD47, inhibit T cell differentiation." (PMID 36481664, 2022).